EXOC5 (exocyst complex component 5)
Description:
Component of the exocyst complex involved in the docking of exocytic vesicles with fusion sites on the plasma membrane.
Synonyms: hSec10; SEC10; SEC10L1; SEC10P; PRO1912
Tractability: PROTAC: ubiquitination databases record sites on it; its protein half-life has been measured.
Gene: Protein-coding gene on chromosome 14 (57,200,507 to 57,268,974, reverse strand). Ensembl gene ENSG00000070367.
Subcellular location: Cytoplasm; Midbody
Subcellular location (Human Protein Atlas): Vesicles
Pathways (Reactome):
Metabolism of proteins: Insulin processing
Organelle biogenesis and maintenance: VxPx cargo-targeting to cilium
Vesicle-mediated transport: Translocation of SLC2A4 (GLUT4) to the plasma membrane
Gene Ontology:
Molecular function: protein binding; small GTPase binding
Biological process: exocytosis; Golgi to plasma membrane transport; membrane fission; mitotic cytokinesis; post-Golgi vesicle-mediated transport; kidney development; protein localization to plasma membrane
Cellular component: midbody; cytoplasm; cytosol; exocyst
Genetic constraint (gnomAD): Loss-of-function variants: 3 observed, 16.14 expected, observed/expected ratio (o/e) 0.19, 90% interval 0.084 to 0.48. The upper end of that interval is the gene's LOEUF score, 0.48, which puts it in group 2 of 6, group 1 being the genes least tolerant of losing a copy. Missense variants: 183 observed, 251.59 expected, observed/expected ratio (o/e) 0.73, 90% interval 0.64 to 0.82. Synonymous variants: 89 observed, 86.98 expected, observed/expected ratio (o/e) 1.02, 90% interval 0.86 to 1.22.
Homologues: Orthologues: chimpanzee EXOC5 (99% identical), dog EXOC5 (99% identical), pig EXOC5 (99% identical), macaque EXOC5 (99% identical), mouse Exoc5 (98% identical), rat Exoc5 (98% identical), guinea pig EXOC5 (95% identical), tropical clawed frog exoc5 (91% identical), zebrafish exoc5 (83% identical), Drosophila melanogaster Sec10 (43% identical), Caenorhabditis elegans sec-10 (36% identical).
Diseases named in the same sentence as EXOC5 in open-access papers:
EXOC5 is named in the same sentence as 21 diseases in open-access papers, as found by Europe PMC text mining. Sharing a sentence is not in itself a finding about the gene and the disease. The quoted sentences say what the papers report.
hydronephrosis (3 papers, 2015 to 2022). Collection of urine in the renal pelvis that results in dilatation of the renal pelvis and calyces. "With the obstruction prevented, we observed that hydronephrosis was avoided in these Exoc5 CKO embryos as well." (PMID 36004645, 2022). "Exoc4/Sec8-/- mice initiate gastrulation but die shortly afterward, Exoc1/Sec3-null mice undergo peri-implantation lethality, and the conditional ablation of Exoc5/Sec10 leads to bilateral hydronephrosis and complete anuria in newborn mice leading to death shortly after." (PMID 36150098, 2022).
obstructive uropathy (2 papers, 2015 to 2022). "The phenotypic mirroring of human COU by the Exoc5 CKO mouse offers a congenital model for deconstructing the molecular mechanisms underlying the onset of obstructive uropathy." (PMID 36004645, 2022). "Taken together, ablation of Exoc5 disrupts autophagic stress response and activates progressive NF-κB signaling, which promotes obstructive uropathy." (PMID 36004645, 2022).
acute kidney injury (1 paper, 2026). Sudden and sustained deterioration of the kidney function characterized by decreased glomerular filtration rate, increased serum creatinine or oliguria. "Collectively, these findings indicate that loss of Exoc5 impairs PTC regeneration and exacerbates fibrosis in the injured kidney, suggesting its therapeutic potential in preventing the transition from acute kidney injury (AKI) to chronic kidney disease (CKD)." (PMID 42031724, 2026).
aortic valve stenosis (1 paper, 2020). Aortic valve stenosis (AVS) is a condition characterized by narrowing of the heart's aortic valve opening. "This recent study also indicates that removal of exocyst complex component 5 (Exoc5), specific of the endocardium, was enough to cause BAV malformation and promote calcified aortic valve stenosis in adulthood." (PMID 32973551, 2020).
autism (1 paper, 2024). Persistent deficits in social interaction and communication and interaction as well as a markedly restricted repertoire of activity and interest as well as repetitive patterns of behavior. "Regulatory inference using the Genie3 algorithm identified direct regulation of IGF1 by SIK1, MFRP, CHD7, NIPBL, EXOC5, and ARID2, with SIK1 and SPARCL1 significantly downregulated in autism brain organoids, potentially affecting IGF1 expression." (PMID 39376742, 2024).
Impaired glucose tolerance (1 paper, 2021). An abnormal resistance to glucose, i.e., a reduction in the ability to maintain glucose levels in the blood stream within normal limits following oral or intravenous administration of glucose. "Additionally, male Exoc5-SMKO mice had impaired glucose tolerance and lower serum insulin levels." (PMID 33647317, 2021). "Taken together, skeletal muscle knockout of Exoc5 resulted in increased fasting glycemia and impaired glucose tolerance, but did not impair a functional insulin signaling pathway activation." (PMID 33647317, 2021).
inflammatory breast carcinoma (1 paper, 2021). An advanced, invasive breast adenocarcinoma characterized by the presence of distinct changes in the overlying skin. "Furthermore, increased EXOC5 mRNA levels were previously correlated with E-cadherin overexpression within the lymphovascular embolus of inflammatory breast cancer." (PMID 34493070, 2021).
Ureteral obstruction (1 paper, 2026). Obstruction of the flow of urine through the ureter. "Unilateral ureteral obstruction (UUO) led to kidney fibrosis with decreased Exoc5 expression, and Exoc5 knockout worsened the fibrosis." (PMID 41781492, 2026).
infection (2 papers, 2025). The state of being infected such as from the introduction of a foreign agent such as serum, vaccine, antigenic substance or organism. "The over-expression of EXOC5 (a.k.a Sec10) stimulated the infection of HSV-1 and VSV." (PMID 41292918, 2025).
cancer (1 paper, 2021). A tumor composed of atypical neoplastic, often pleomorphic cells that invade other tissues. "Analyzing protein–protein interaction network in STRING database, SLC2A4 also participates in the translocation of SLC2A4 (GLUT4) to the plasma membrane and protein localization to plasma membrane through enriched proteins such as EXOC5 and C2CD5, which play an important role in human cancers." (PMID 34488531, 2021).
tumor (1 paper, 2019). "Our analysis identified several candidate genes, including EXOC5, PPP2R5E, and SOS2, and showed that PPP2R5E and SOS2 expression levels correlated with MuD level in tumor cells to some extent." (PMID 31616474, 2019).
EXOC5 also shares sentences with these, for which no sentence is quoted: autosomal dominant polycystic kidney disease (2 papers); chronic kidney disease (1); Cognitive impairment (1); cyst (1); heart failure (1); high blood pressure (1); Insulin resistance (1); Kidney Cyst (1); retinal dystrophies (1); viral infection (1).